DEFA8P (defensin alpha 8, pseudogene)
Synonyms: DEFAP1
Gene: Transcribed unprocessed pseudogene on chromosome 8 (6,950,726 to 6,951,599, reverse strand). Ensembl gene ENSG00000223629.
Diseases named in the same sentence as DEFA8P in open-access papers:
DEFA8P is named in the same sentence as 1 disease in open-access papers, as found by Europe PMC text mining. Sharing a sentence is not in itself a finding about the gene and the disease. The quoted sentences say what the papers report.
Cryptococcal meningitis (1 paper, 2019). Meningeal inflammation produced by cryptococcus neoformans, an encapsulated yeast that tends to infect individuals with acquired immunodeficiency syndrome and other immunocompromised states. "The expression of the lncRNAs, ECRP, LINC00968, DPY19L1p1, DEFA8P, and DEFT1P2 was higher but the expression of the lncRNAs DDX11L10 and MTMR9LP was lower in cryptococcal meningitis patients than in healthy controls, which was consistent with the chip analysis results." (PMID 30767376, 2019).